CDKN1C (cyclin dependent kinase inhibitor 1C)
Description:
Potent tight-binding inhibitor of several G1 cyclin/CDK complexes (cyclin E-CDK2, cyclin D2-CDK4, and cyclin A-CDK2) and, to lesser extent, of the mitotic cyclin B-CDC2. Negative regulator of cell proliferation. May play a role in maintenance of the non-proliferative state throughout life.
Synonyms: KIP2; P57; BWCR; BWS; WBS; p57Kip2
Tractability: No criterion of Open Targets' tractability assessment is met for any kind of drug.
Gene: Protein-coding gene on chromosome 11 (2,883,213 to 2,885,775, reverse strand). Ensembl gene ENSG00000129757.
Subcellular location: Nucleus
Subcellular location (Human Protein Atlas): Nuclear bodies; Nucleoplasm; Cytosol
Pathways (Reactome):
Cell Cycle: Cyclin D associated events in G1
Disease: Defective binding of RB1 mutants to E2F1,(E2F2, E2F3)
Gene Ontology:
Molecular function: cyclin-dependent protein serine/threonine kinase inhibitor activity; molecular function inhibitor activity; protein binding; protein-containing complex binding
Biological process: negative regulation of epithelial cell proliferation; positive regulation of transforming growth factor beta receptor signaling pathway; negative regulation of mitotic cell cycle; regulation of cell cycle
Cellular component: cytoplasm; nucleus
Genetic constraint (gnomAD): Loss-of-function variants: 7 observed, 4.32 expected, observed/expected ratio (o/e) 1.62, 90% interval 0.84 to 1.94. That is too few expected variants to judge how well the gene tolerates losing a copy. Missense variants: 316 observed, 237.87 expected, observed/expected ratio (o/e) 1.33, 90% interval 1.21 to 1.46. Synonymous variants: 213 observed, 120.89 expected, observed/expected ratio (o/e) 1.76, 90% interval 1.57 to 1.94.
Gene-disease validity (ClinGen):
ClinGen rates the evidence that CDKN1C causes each of these diseases.
Beckwith-Wiedemann syndrome due to CDKN1C mutation (autosomal dominant): Strong.
Homologues: Orthologues: macaque CDKN1C (96% identical), chimpanzee CDKN1C (75% identical), pig CDKN1C (57% identical), mouse Cdkn1c (54% identical), rat Cdkn1c (52% identical), dog CDKN1C (51% identical), zebrafish cdkn1ca (23% identical), tropical clawed frog cdknx (18% identical), zebrafish cdkn1cb (16% identical). Paralogues in human: CDKN1B (19% identical), CDKN1A (13% identical).
Diseases named in the same sentence as CDKN1C in open-access papers:
CDKN1C is named in the same sentence as 193 diseases in open-access papers, as found by Europe PMC text mining. Sharing a sentence is not in itself a finding about the gene and the disease. The quoted sentences say what the papers report.
Beckwith-Wiedemann syndrome (38 papers, 2007 to 2025). Beckwith-Wiedemann syndrome (BWS) is a genetic disorder characterized by overgrowth, tumor predisposition and congenital malformations. "CDKN1C is a well-known locus for Beckwith-Wiedemann syndrome-associated rearrangements—the first balanced rearrangements clustering 100-kb from CDKN1C were described nearly 30 years ago." (PMID 38776926, 2024). "As a gene associated with suppressing tumor growth, CDKN1C is linked to a variety of human cancers and Beckwith-Wiedemann Syndrome." (PMID 38028594, 2023). "In patients with Beckwith-Wiedemann syndrome and CDKN1C mutations, an extended phenotype including ear pits and polydactyly has been described." (PMID 33208384, 2022). "Reduction in the activity of CDKN1C is implicated in Beckwith-Wiedemann syndrome, an overgrowth syndrome." (PMID 33282601, 2020). "Although loss-of-function of CDKN1C is known to cause macrosomia as part of Beckwith-Wiedemann Syndrome, it is only in the past eight years that “gain-of-function” variants in CDKN1C have been shown to cause growth restriction and IMAGe syndrome." (PMID 31497289, 2019). "Consistent with its role in growth and development, maternally-inheritedloss-of-function variants in CDKN1C are found in approximately 5–10% of individuals with the “overgrowth” condition, Beckwith-Wiedemann Syndrome (BWS) (OMIM130650) (Eggermannet al., 2014)." (PMID 31497289, 2019). "The loss or gain in function of CDKN1C in humans is already implicated in the childhood growth disorders Beckwith-Wiedemann Syndrome, IMAGe syndrome and SRS, recapitulated to some extent in animal models." (PMID 30213134, 2018). "Some genetic alterations suggest a role for increased dosage of the imprinted CYCLIN DEPENDENT KINASE INHIBITOR 1C (CDKN1C) gene, often mutated in IMAGe Syndrome and Beckwith-Wiedemann Syndrome (BWS)." (PMID 26963625, 2016). "Loss-of-function mutations in CDKN1C have been identified in 5-10% of individuals with Beckwith-Wiedemann syndrome (BWS), an overgrowth disorder with features that are the opposite of IMAGe syndrome." (PMID 25861374, 2015). "CDKN1C is a negative regulator of cell growth and proliferation and mutations are also implicated in the pathogenesis of Beckwith Wiedemann Syndrome, characterised by pre- and post-natal overgrowth." (PMID 22431966, 2012). "50% of patients with the overgrowth disorder Beckwith Wiedemann syndrome commonly have epigenetic silencing of CDKN1C caused by a methylation defect within IC2 on 11p15.5." (PMID 19221586, 2009). "Interestingly, a point mutation in the CDKN1C gene was found in a family with several features consistent with IMAGe syndrome, a growth and developmental disorder similar to Beckwith-Wiedemann Syndrome, as well as an early-adult-onset form of diabetes." (PMID 33986727, 2021). "The human imprinted gene CDKN1C is the most frequently silenced or mutated gene in the imprinting genetic disorder Beckwith-Wiedemann syndrome (BWS); aberrant imprinting of IGF2 has also been shown to interact with CDK1C in this imprinting disorder." (PMID 36633189, 2023). "We have previously shown the opposing effects of variants in CDKN1C/CDKN1C, whereby gain of function of this cell cycle repressor is associated with adrenal hypoplasia and IMAGe syndrome and loss of function is associated with Beckwith-Wiedemann syndrome with an adrenal neoplasm risk." (PMID 37440461, 2023). "About 5–10% of cases exhibiting Beckwith-Wiedemann syndrome (BWS), an overgrowth syndrome characterized by macrosomia, macroglossia, and abdominal wall defects, are caused by loss-of-function mutations of cyclin-dependent kinase inhibitor 1C (CDKN1C, p57kip2)." (PMID 30602375, 2019). "In many Beckwith-Wiedemann Syndrome patients, the ICR2 region at 11p15 is hypomethylated on both alleles, causing loss of expression of CDKN1C and is linked with an increase in proliferation of beta cells." (PMID 33986727, 2021).
Beckwith-Wiedemann syndrome (continued). "Beckwith-Wiedemann syndrome can be caused by disorders of methylation affecting imprinted genes within chromosome 11p15.5 containing IGF2 and CDKN1C, both of which appeared in our analyses." (PMID 33682876, 2021). "Most notably, both IGF2 and the maternally expressed cell cycle inhibitor CDKN1C can contribute to the overgrowth disorders seen in Beckwith-Wiedemann syndrome and there is evidence that changes in Igf2 expression can influence expression of Cdkn1c." (PMID 25551289, 2014). "Loss of expression of Cdkn1c through maternal inheritance of a targeted deletion results in severe developmental abnormalities, similar to that seen in humans with loss of CDKN1C in Beckwith-Wiedemann syndrome (BWS)." (PMID 17517131, 2007). "CDKN1C is implicated in syndromes associated with intrauterine growth restriction (IUGR) (IMAGE syndrome) and over-growth (Beckwith-Wiedemann syndrome); one of the birth weight SNPs is located 47 146 bp from this gene within an intron of KCNQ1, which is not linked to DDs." (PMID 33682876, 2021). "Using a TALEN dependent targeting of TET1, Kaestner and colleagues simulated the DNA methylation patterns associated with beta cell hyper-proliferation in Beckwith Wiedemann Syndrome (BWS), where hypomethylation of the CDKN1C locus leads to reduced p57Kip2 and beta-cell hyper-proliferation." (PMID 34025578, 2021). "Beckwith-Wiedemann syndrome (BWS, OMIM 130650), either sporadic (>85%) or familial (<15%), is caused by mutation or deletion of imprinted genes CDKN1C, H19 and LIT1 as well as by hypermethylation in the H19/IGF2-imprinting control region within the chromosome 11p15.5 region." (PMID 29190888, 2017). "For example, Beckwith-Wiedemann syndrome can result from increased expression of insulin-like growth factor 2 (IGF2), a paracrine growth factor, and/or from decreased expression or inactivating variants in cyclin-dependent kinase inhibitor 1c (CDKN1C), which regulates cell cycle progression." (PMID 36927955, 2023). "For example, Beckwith-Wiedemann Syndrome (BWS) with RMS involves dysregulation or alteration of imprinted genes in the 11p15.5 chromosomal region, including IGF2, H19, and CDKN1C (p57/KIP2)." (PMID 26420980, 2015). "Beckwith-Wiedemann syndrome (BWS) is a fetal overgrowth and human imprinting disorder resulting from the deregulation of a number of genes, including IGF2 and CDKN1C, in the imprinted gene cluster on chromosome 11p15.5." (PMID 19300480, 2009). "Known human neurological disorders associated with the networks, particularly network 2, include X-linked lissencephaly (Online Mendelian Inheritance in Man [OMIM:300067]; DCX), juvenile onset dystonia ([OMIM:607371]; ACTB) and Beckwith-Wiedemann syndrome ([OMIM:130600]; CDKN1C)." (PMID 19799774, 2009). "In contrast to the functionally inactivating mutations reported in the congenital overgrowth disorder Beckwith-Wiedemann syndrome (BWS, MIM 130650), studies suggest increased protein stability in IMAGe syndrome consistent with a role for CDKN1C in growth restriction." (PMID 27798108, 2016).
breast carcinoma (33 papers, 2004 to 2024). "Consistent with the overexpression of EZH2 in a variety of human cancers including breast cancer, CDKN1C in these cancers is downregulated, and breast tumors expressing low levels of CDKN1C are associated with a poor prognosis." (PMID 19340297, 2009). "We determined rates of allele imbalance or loss of heterozygosity (AI/LOH) in CDKN1C, using an intronic polymorphism, and in the surrounding 11p15.5 region in 82 breast cancers." (PMID 18325103, 2008). "Its family members (CDKN1A/p21CIP1 and B/p27KIP1) have been implicated in breast cancer, but information about CDKN1C's role is limited." (PMID 18325103, 2008). "Furthermore, the CDKN1C expression is detected to be associated with age and tumor size in The Cancer Genome Atlas (TCGA) cohort containing 708 cases of breast cancer." (PMID 32318583, 2020). "Our findings suggest that Polycomb protein EZH2-mediated H3K27me3 might be the key chromatin mark associated with the transcriptional repression of CDKN1C in breast cancer cells." (PMID 19340297, 2009). "Finally, we show that the downregulation of CDKN1C by EZH2 in breast cancer is associated with a poor disease outcome." (PMID 19340297, 2009). "Finally, this study found a strong association between CDKN1C and breast cancer, but cannot determine causality." (PMID 18325103, 2008). "The goal of this study is to examine whether CDKN1C is implicated in human breast cancers in vivo." (PMID 18325103, 2008). "For example, CDKN1C as a prognostic biomarker correlated with immune infiltrates and therapeutic responses in breast cancer patients." (PMID 38520027, 2024). "Previous evidence has shown that downregulated CDKN1C correlates with poor overall survival, immune infiltration and therapeutic response in breast cancer patients." (PMID 35739271, 2022). "CDKN1C is frequently downregulated and plays a tumor suppressor role in many cancers including liver cancer, pancreatic cancer, lung cancer and breast cancer." (PMID 35612714, 2022). "Abnormal expression of CDKN1C plays a role in breast cancer, gastric cancer, glioma and other cancers." (PMID 32117949, 2020). "CDKN1C has been identified as a tumor suppressor due to its diminished expression and functions of blocking biological signs of progress of breast cancer." (PMID 32308561, 2020). "One is CDKN1C-p57Kip2, a protein reduced or lost in the majority of breast cancers, possibly through ER-dependent mechanisms." (PMID 29301281, 2018). "In breast cancer, several lines of evidence have implicated overexpression of EZH2 and repression of tumor suppressors such as KRT5, KRT6, CDH3, RAD51 paralogs, CDKN1C, FOXC1, Wnt/β-catenin signaling (c-Myc, Cyclin D1, Axin2), RKIP and KLF2." (PMID 27835578, 2016). "The activation of estrogen signaling in breast cancer cells appeared to enhance expression of Kcnq1ot1 and repression of CDKN1C (cyclin-dependent kinase inhibitor 1C) that is concomitant with loss of Kcnq1ot1 methylation in its promoter CpG island." (PMID 26378581, 2015). "KCNQ1OT1 is induced by estrogen in estrogen receptor-alpha (ERα) expressing breast cancer cells and further mediate CDKN1C repression through epigenetic repression." (PMID 26278472, 2015). "We used receiver operator characteristic (ROC) analysis to compare the methylation status of BANK1 and CDKN1C in breast brain metastasis samples to a series of 48 early-stage primary breast cancer samples." (PMID 24489661, 2014). "We also demonstrate the prognostic value of EZH2-mediated CDKN1C repression in breast cancer and suggest its clinical significance for EZH2-targeted cancer therapeutics." (PMID 19340297, 2009). "Taken together, our study reveals a novel epigenetic mechanism governing CDKN1C repression in breast cancer." (PMID 19340297, 2009). "This indicates that both EZH2 and its target gene CDKN1C can be used to predict breast cancer outcome." (PMID 19340297, 2009).
breast carcinoma (continued). "In this study, we report that the CDKN1C is repressed in breast cancer by multiple epigenetic mechanisms." (PMID 19340297, 2009). "The search results revealed that EZH2 is consistently upregulated in multiple human cancer types including breast cancer, while CDKN1C is downregulated in these tumors." (PMID 19340297, 2009). "Taken together, we conclude that histone modifications play a predominate role in epigenetic repression of CDKN1C in breast cancer cells." (PMID 19340297, 2009). "In this study, we show that CDKN1C is repressed in breast cancer cells mainly through histone modifications." (PMID 19340297, 2009). "Taken together, these data led us to investigate CDKN1C's potential role as a tumor suppressor in breast cancer in vivo." (PMID 18325103, 2008). "CDKN1A and B play important and complex roles in breast cancer, but knowledge of CDKN1C's role is limited." (PMID 18325103, 2008). "CDKN1C is expressed in normal epithelium of most breast cancer cases, mainly in the myothepithelial layer." (PMID 18325103, 2008). "For example, L1CAM, GATA4, CCNB1, CDKN1C, and FEN1 have been reported for their association with breast cancer: L1CAM was shown to inhibit the growth of breast carcinoma cells." (PMID 18237428, 2008). "CDKN1C showed gain of DNA methylation and downregulated expression in breast cancers." (PMID 35739271, 2022). "CDKN1C is a cancerous lump restrainer gene, which is down-regulated in studies related to gastric cancer, bladder cancer, pancreatic cancer, lung cancer, and breast cancer, and low expression points are connected with reduced prediction in sufferers." (PMID 32318583, 2020). "For instance, CDKN1C is targeted by H3K27me3 in breast cancer cells." (PMID 31367252, 2019). "Particularly, a downregulation of CDKN1C is generally reported in cancer including gastric and urothelial cancer, pancreatic adenocarcinomas, adrenocortical, lung, and breast cancer as well as several leukemias." (PMID 29614816, 2018). "Examination of CDKN1C expression from our breast cancer cell lines gene expression database indicates that CDKN1C expression displayed varied levels of expression but in general was reduced in most of the breast cancer cell lines (except the MDA-MB-231 cells) as compared to MCF10A cells." (PMID 19340297, 2009). "We next set out to determine whether histone modifications are responsible for CDKN1C repression in breast cancer." (PMID 19340297, 2009). "Evidence also exists for CDKN1C silencing in lung and breast cancer by promoter methylation." (PMID 19221586, 2009). "CDKN1C's role in breast cancer in vivo has been considered previously, but data are limited." (PMID 18325103, 2008). "11p15 undergoes allele imbalance (AI) or loss of heterozygosity (LOH) in 35–40% of breast cancers, but CDKN1C does not appear to be commonly mutated or rearranged." (PMID 18325103, 2008). "Twenty breast cancer cases were examined for CDKN1C protein levels using IHC." (PMID 18325103, 2008). "Thus, the combination of both EZH2 and CDKN1C may be more predictive of breast cancer recurrence than either one alone." (PMID 19340297, 2009). "Second, CDKN1C may be regulated by estradiol in mammary carcinoma cells." (PMID 18325103, 2008). "For instance, in breast cancer, raised levels of PRC2 leads to high levels H3K27 methylation in the promoter regions of FOXC1, E-cadherin, RAD51, RUNX3 and CDKN1C (p57kip2)." (PMID 27845897, 2017). "We next treated these breast cancer cell lines with DZNep, TSA, or Aza alone or in various combinations and performed quantitative RT-PCR to assess the changes of CDKN1C expression upon these treatments." (PMID 19340297, 2009). "It has been shown that miR-221 and miR-222 functionally target and inhibit the expression of tumor suppressor genes (such as CDKN1B/p27 and CDKN1C/p57) and oncogenes (such as BCL2L1 and ER) in various cancers, including glioblastoma, hepatocellular carcinoma, breast cancer, and PCa." (PMID 37370750, 2023).
breast carcinoma (continued). "To validate this finding, we first examined the relationship between the DNA methylation status of the CDKN1C promoter and the levels of CDKN1C expression in various breast cancer cell lines as well as the non-cancerous breast epithelial cell line (MCF10A)." (PMID 19340297, 2009). "Furthermore, we show that breast cancer expressing both higher EZH2 and lower CDKN1C show a much poorer disease-free survival rate (P = 0.001046) compared to patients with lower EZH2 and higher CDKN1C." (PMID 19340297, 2009). "Lack of dominate effect of DNA methylation, together with RT-PCR analysis, indicate that CDKN1C expression in breast cancer is maintained at low or basal levels rather than completely silenced." (PMID 19340297, 2009). "We predict that breast cancer patients with higher EZH2 and lower CDKN1C might receive the greatest benefit from cancer therapeutic targeting of EZH2-mediated gene repression." (PMID 19340297, 2009). "Furthermore, L1CAM, CDKN1C, and FEN1, which have been reported to be relevant to breast cancer – the most sensitive subtype to docetaxel among the nine NCI-60 cancer subtypes – were clustered just next to the drug vector." (PMID 18237428, 2008). "However, recent reports demonstrate CDKN1C in breast cancer is observed to be intensely down-regulated equated with normal tissue." (PMID 32318583, 2020). "The status of CDKN1C expression could also be tested in other cancers as 5-azacytidine plus entinostat regimen has been successfully tested on patients with AML arising after chemotherapy or radiation therapy, breast cancer and colorectal cancer." (PMID 30310057, 2018). "Thus, the detection of a strong H3K4me3 in the CDKN1C promoter is consistent with the lack of DNA methylation in the vicinity of the CDKN1C promoter as we observed in breast cancer cells." (PMID 19340297, 2009). "We are not aware of any reports examining CDKN1C protein expression in human breast cancers." (PMID 18325103, 2008). "Finally, CDKN1C may be regulated by epigallocatechin-3-gallate (EGCG), a polyphenol in green tea with anti-oxidant effects that may have cancer-suppressive effects in general, and in breast cancer in particular." (PMID 18325103, 2008). "We find that the CDKN1C gene does not appear to undergo frequent genetic alteration, as measured by AI/LOH, but that mRNA and protein levels are decreased in the large majority of breast cancers compared to paired normal epithelium." (PMID 18325103, 2008).